CD4 (CD4 molecule)
Diseases named in the same sentence as CD4 in open-access papers (continued):
Sharing a sentence is not in itself a finding about the gene and the disease.
Thrombocytopenia (continued). "Compared with αβ TCR-type T-LGL leukemia, γδ-type T-LGL leukemia patients have more obvious thrombocytopenia, lower absolute neutrophil count, and higher CD4 and CD8 double-negative ratios." (PMID 32612945, 2020). "The study objectives were to assess the clinical efficacy, immune function (including CD3+, CD4+, CD8+, CD4+/CD8+, natural killer (NK) cell count, IgA, IgG, and IgM), adverse events such as nausea and vomiting, thrombocytopenia, and leukopenia of combination therapy in patients with advanced NSCLC." (PMID 32047528, 2020). "CBC: Adult patients may have mild leucopenia, lowish absolute lymphocyte counts (with decreased CD4+ and CD8+ subsets), and thrombocytopenia." (PMID 33224906, 2020). "However, studies showed that thrombocytopenia is more prevalent and severe among patients with more advanced HIV disease or lower CD4+ T cell count." (PMID 30759131, 2019). "The aim of our study was to assess the burden of thrombocytopenia according to antiretroviral therapy (ART), viremia and CD4-lymphocyte count of PLHIV in view of limiting the occurrence of this haematological disorder and optimizing the management of PLHIV in Yaoundé, Cameroon." (PMID 31554515, 2019). "And the meta-assay results suggested that SFI intervention improves the clinical effect and the quality of survival (KPS), strengthens cellular immune function (CD3+, CD4+, CD4+/CD8+ and NK+), and reduces the adverse events such as leukocytopenia, thrombocytopenia and gastrointestinal toxicity." (PMID 28953950, 2017). "We also examined the relationship of thrombocytopenia with HIV viral load and CD4 count." (PMID 26498280, 2015). "As CD4 counts of HIV patients decreasing, they have more likely to have thrombocytopenia." (PMID 24387326, 2014). "According to the present study, as immunity of a patient decreasing, thrombocytopenia was more prevalent rather than HIV positive patients who have relatively high CD4 count." (PMID 24387326, 2014). "Lack of adherence was either due to non-compliance, co-morbidity or concomitant medication, low CD4 counts, or severe thrombocytopenia before or during treatment." (PMID 16916475, 2006). "Finally, we summarized the quality of ORR, DCR, QOL, myelosuppression, neutropenia, thrombocytopenia, gastrointestinal toxicity, hepatorenal toxicity, neurotoxicity, CD3+ T cells, CD3+ CD4+ T cells, and CD4+/CD8+ T cell ratios as “moderate” and other indicators as “low to very low”." (PMID 34122057, 2021). "However, the increase in prevalence of thrombocytopenia with decreased CD4 cell count was not statistically significant." (PMID 29760930, 2018). "However, the increase in prevalence of thrombocytopenia with decreased CD4 cell count was not statistically significant (P >0.05)." (PMID 24387326, 2014). "Chemotherapy and MMC in particular, was applied less frequently and with worse adherence in the HIV-seropositive patients either due to non-compliance, co-morbidity or concomitant medication, low CD4 counts, or severe thrombocytopenia before or during treatment." (PMID 16916475, 2006). "Furthermore, they also presented with minor clinical features indicative of an autoinflammatory disorder, such as discrete leukopenia (with a lack of B cells in patient 2 and low CD4+ T cells and natural killer cells in patient 3), thrombocytopenia, and the presence of anti-nuclear antibodies." (PMID 36672163, 2023). "Most HIV-1/HTLV-1 co-infected individuals are more likely to develop myelopathy, bronchitis, thrombocytopenia, urinary tract infections, or opportunistic diseases than HIV-1 mono-infected individuals, regardless of ethnicity, age, or CD4+ T-cell count." (PMID 40284988, 2025). "In this case, the patient was already on ART and had an undetectable viral load, making IRIS-related thrombocytopenia less likely, favoring TTP diagnosis in rare instances of normal CD4 count." (PMID 39445270, 2024).
Thrombocytopenia (continued). "Furthermore, patients with thrombocytopenia had significantly lower CD4 counts (median: 163 cells/μL, IQR: 64.25–313.75) compared to those without thrombocytopenia (median: 441 cells/μL, IQR: 251–672) (p = 0.004)." (PMID 38005902, 2023).
HCMV infection (102 papers, 2006 to 2026). "Protection against congenital transmission in women with primary HCMV infection is associated with early emergence of CD4 T cells." (PMID 38561339, 2024). "The combination of chronic HCMV infection, terminally differentiated T cells and inverted CD4:CD8 T cell ratio results in an “immune risk profile” (IRP) that has been strongly associated with immunosenescence and early death in the elderly." (PMID 33808294, 2021). "The presence of large numbers of CD28null CD4 T cells in such conditions suggests a pathogenic role of this subset and indirectly one of CMV infection." (PMID 30984377, 2019). "A key component of the IRP, which is associated with HCMV infection, is the inversion of the CD4:CD8 ratio (<1), we only saw this phenomenon in 10% of the seropositive donor group." (PMID 28694811, 2017). "There was a strong association between a previous CMV infection and the presence and percentage of CD4+CD28null T cells (0.33 vs 13.8, P < 0.001)." (PMID 28084533, 2017). "The IRP, was associated with persistent cytomegalovirus infection and characterized by inverted CD4/CD8 ratio and related to expansion of terminally differentiated effector memory T cells (TEMRA phenotype)." (PMID 22415616, 2013). "The case of a D+R- hand transplant recipient with recurrent episodes of disseminated HCMV infection associated with impaired HCMV-specific CD4+ and CD8+ T cell response is described." (PMID 18798988, 2008). "However, our data demonstrate the suitability of pp65-IGRA for the quantification of HCMV-specific CD4+ T-cell responses and its potentiality in identifying patients at risk for, or protected from, HCMV infection after transplantation." (PMID 40443680, 2025). "The long-term shedding of the virus in saliva during HCMV infection in children could be caused by long-lasting deficiency of CD4 T cells in children." (PMID 39134803, 2024). "Finally, HCMV infection has been positively associated with CD4+CD28- T-cell expansion and high cardiovascular disease (CVD) mortality risk among RA patients, further confirming a direct causal link between HCMV and vascular damage in AD." (PMID 33567734, 2021). "Remarkably, T cell development was enhanced in thymus upon HCMV infection, which was associated with the expansion of memory CD4+ and CD8+ T cells in secondary lymphatic tissues and up-regulation of the programmed cell death (PD)-1 activation marker on T cells." (PMID 32079250, 2020). "In addition to causing a slower increase of fetal CD4+ T cells, CMV infection in utero also appears to cause an oligoclonal expansion of CD4+ T cells in the infected newborn." (PMID 32509591, 2020). "The combination of chronic HCMV infection, late-differentiated T cells and inverted CD4:CD8 T cell ratio and are all components of an “immune risk profile” (IRP) that has been associated with immunosenescence, cognitive decline, frailty and early death in the elderly." (PMID 32582177, 2020). "A previous CMV infection, however, was highly associated with the presence of CD4+CD28null T cells." (PMID 28084533, 2017). "It has been proposed that the association of CMV infection with cardiovascular disease may be a direct result of pathology caused by the large expansion of CD4+ CD28-negative T cell populations commonly seen in CMV-infected individuals." (PMID 28647908, 2017). "However, there was a strong association between a previous CMV infection and the presence and percentage of CD4+CD28null T cells (0.33 vs 13.8, P < 0.001)." (PMID 28084533, 2017). "Immuno-virologic discordance has been defined and studied in multiple settings mainly in resource-rich countries and has been associated with co-infections (especially Cytomegalovirus infections), age, lower baseline CD4 cell count, poor adherence and high mortality." (PMID 23452915, 2013).
HCMV infection (continued). "Cytomegalovirus infection is associated with expansion of these cells, but only a minority of CD4+CD28null T cells could be identified as specific for cytomegalovirus antigen." (PMID 24288592, 2013). "The CD4+ T cell response against cytomegalovirus is of interest for several reasons, related primarily to the unusual magnitude and phenotype of virus-specific cells, and also their potential role in the vascular damage that is reported in association with CMV infection in older people." (PMID 27606804, 2016). "A study of chronic cytomegalovirus infection in macaques demonstrated that the antigen-specific T cell population was highly enriched within the CD4+CD8α+ DP T cells relative to CD4+ SP T cells." (PMID 39912921, 2025). "In the first part of this review, we overview the humoral response to HCMV, followed by sections on the response of NK cells, CD8+ T cells, CD4+ T cells and the growing field of unconventional T cell subsets to HCMV infection." (PMID 41194662, 2025). "These CD4 T cells secrete IL-10 in response to IL-27, which is induced by type I IFNs secreted in response to CMV infection." (PMID 39134803, 2024). "For example, in transplant patients, the long-term protection from HCMV infection is achieved when the CD4+ T-cell response is restored; moreover, CD8+ T cells do not appear to be protective in the absence of the CD4+ T-cell counterpart." (PMID 39336935, 2024). "Previous research has shown that a decrease in CD4+ cell counts (<500 cells/mm3) was observed in conjunction with active cytomegaloviral infection." (PMID 38932140, 2024). "Cytomegalovirus infection and pneumocystis infection were mostly found in Endotype3, along with the lowest CD4/CD8 ratio (overall P = 0.003, 0.018, and < 0.001, respectively)." (PMID 38533498, 2024). "In early cases, no significant variations were observed (p-0.384), but in later rejected cases with persistent HCMV infection, CD-4+ counts were significantly reduced (p < 0.001) compared to non-rejected patients." (PMID 38932140, 2024). "It has been demonstrated that natural HCMV infection induces a potent immune response comprising antibodies as well as CD4+ and CD8+ T cells." (PMID 38303144, 2024). "The HCMV CD4+ T cell numbers measured by any of the assays evaluated were predictive of self-resolving HCMV infection." (PMID 39195215, 2024). "We observed that the CD4+ CFC-pp65 pool assay was the best predictor of self-resolving HCMV infection at the time of the HCVM-DNA peak." (PMID 39195215, 2024). "Regarding the prediction potential of T cells in HCMV infection, most researchers have investigated other members of CD4+ T cells than recently identified Th22 cells." (PMID 37403036, 2023). "As central orchestrators of the immune system, CD4+ T cells have an important role in HCMV infection." (PMID 37403036, 2023). "In pregnant women with primary CMV infection, the presence of HCMV-specific memory CD4 + T-cells has been linked with rapid control of HCMV infection and a lower risk for vertical transmission of the virus to the fetus." (PMID 37376633, 2023). "During the acute phase of the response to HCMV infection, specific CD4 + T-cells are highly activated and proliferate." (PMID 37376633, 2023). "Previously explained CD4+ subsets such as T helper (Th) 1 have been proven to have a protective role against HCMV infection, while the role of the recently identified Th22 subset has not been described yet." (PMID 37403036, 2023). "Using this coculture model, CD4 T cells can control HCMV infection in RPE cells almost as effectively as can CD8 T cells, as measured by a reduction in the number of GFP-expressing cells, measured via flow cytometry." (PMID 36445084, 2022). "This provides both the first evidence of CD4 T cell control of HCMV infection in epithelial cells and a novel strategy by which HCMV evades it." (PMID 36445084, 2022).
HCMV infection (continued). "Cytotoxic CD4 T cells have been isolated directly from HCMV patients, and IFN-γ-secreting CD4 effector memory T cells are essential for the effective control of HCMV infections." (PMID 36445084, 2022). "There are limited reports on IL-10 secretion by CD8+ T cells in HCMV infection but liver transplant recipients who progressed to CMV disease had increased expression of PD-1 on both CD4+ and CD8+ T cells and increased IL-10 in their plasma." (PMID 36558866, 2022). "This case demonstrates that HAAA induced by cytomegalovirus infection features decreasing CD4+ and increasing CD8+ PBLs as the bone marrow hypoplasia progresses." (PMID 35212305, 2022). "CD4 T cells have been shown to control HCMV infections in vitro in dendritic cells with constitutive MHC class II expression." (PMID 36445084, 2022). "Adaptive immunity is critical for the control of primary HCMV infections, which can later on be enhanced by clonal expansion of activated CD4+ and CD8+ T-cells." (PMID 33567734, 2021). "This study demonstrated that both CMV-specific antibody and CD4+ T cell responses can be boosted after vaccination with a hCMV gB/MF59 vaccine in women with chronic hCMV infection." (PMID 34070277, 2021). "As already discussed, studies in transplant patients have shown the essential role that the CMV-specific CD4+ T cell response plays in successful resolution of active CMV infection in this setting." (PMID 32509591, 2020). "This was in contrast to the CD4+ T cell responses in 8 adults with primary CMV infection, which was high initially and then subsequently decreased." (PMID 32509591, 2020). "In particular, we focus on the importance of both understanding and assessing the full functionality of CMV specific CD4+ T cells responses in patients to minimize the burden of CMV infection in transplantation and congenital infections." (PMID 32509591, 2020). "Here, we present a detailed overview of the evidence from many studies of the specific and direct anti-viral role that CD4+ T cells play in HCMV infections in the healthy and immunocompromised patients." (PMID 32509591, 2020). "In fact, an examination of 44 pregnant women with primary HCMV infection showed that most of these IFN-γ-producing T cells were CD4+." (PMID 32509591, 2020). "Both of them had risk factors for its development, which include low total and CD4+ lymphocyte counts, cytomegalovirus infection, hypogammaglobulinemia, graft rejection, and patient age." (PMID 33171962, 2020). "Our results reveal a novel mechanism potentially involved in the crosstalk between adaptive NK cells and specific memory CD4+ T cells along persistent HCMV infection." (PMID 31001281, 2019). "Our recent work indeed suggests that CMV infection is a major ‘trigger’ for the expansion of CD28null CD4 T cells, increasing frequencies more than 10-fold on average." (PMID 30984377, 2019). "The role of CD4 T cells in controlling cytomegalovirus infection has been discussed controversially." (PMID 30153311, 2018). "Noteworthy, HCMV infections and reactivations also promoted significantly higher frequencies of CD4+/CD25+/FoxP3+/CD45RA− regulatory T cells (Tregs) (INF Vs." (PMID 30524448, 2018). "The condition is directly related to cytomegalovirus infection and CD4 + lymphocyte counts below 200 cells/mm3." (PMID 30020931, 2018). "In the context of human cytomegalovirus infection, a significant proportion of CD4 T cells displays cytotoxic functions." (PMID 29488879, 2018). "The percentage of CD4+CD28null T cells was even higher in AAV patients with a previous CMV infection compared to the percentage of these cells in healthy controls with a previous CMV infection." (PMID 28084533, 2017). "CD4+ T cell responses in CMV infection have been long known as important contributors to control primary infection." (PMID 28265272, 2017). "We found Hobit expression in cytotoxic CD4+ T cells and accumulation of Hobit+ CD4+ T cells after primary hCMV infection." (PMID 28392788, 2017).
HCMV infection (continued). "In acute HCMV infection, the frequency of IL-7Rpos cells in the total CD4+ T-cell memory compartment slightly decreased with respect to HCMV-naïve donors and then increased towards the basal level (remote infections)." (PMID 29112951, 2017). "We describe that the CD4+ T cells that accumulate after primary hCMV infection in transplant patients express Hobit, suggesting that upregulation of Hobit is an integral part of the cytotoxic CD4+ T cell response against hCMV." (PMID 28392788, 2017). "While the role of MHC I CD8+ T-cell responses against CMV is clearly evident, there is increasing evidence that CD4+ T-cells are also integral to the control of CMV infection and prevent against CMV disease." (PMID 28428537, 2017). "In mice and humans, it has been shown that cytotoxic CD4+ T cells play protective roles in cytomegalovirus (CMV) infections." (PMID 28392788, 2017). "It is clear that primary human cytomegalovirus (HCMV) infection elicits a series of robust cell-mediated immune responses initially by innate NK cells, followed by adaptive CD4+ and CD8+ T cells and B cell high avidity neutralizing antibodies." (PMID 28647908, 2017). "One hallmark of latent HCMV infection is the progressive and substantial expansion of HCMV-specific memory CD8+ T cells over time, with HCMV-specific memory CD4+ T cells accumulating to a lesser extent." (PMID 28082969, 2016). "CMV-specific CD4+ T cells are also critical effector populations in the control of CMV infection where they maintain function of virus-specific CD8+ T cells and suppress viral replication at specific tissue sites." (PMID 27606804, 2016). "In children with primary HCMV infection, virus shedding in urine (a measure of viral load) correlated with delayed CD4 T cell responses." (PMID 26599878, 2015). "In infections with persistently low antigen concentrations, e.g., latent asymptomatic cytomegalovirus infection, CD4+ T-cells secreting IFN-γ only, IFN-γ/IL-2, or IL-2 only are detected." (PMID 25729380, 2015). "In vitro, SmyleDCpp65 resisted HCMV infection, activated CD4+ and CD8+ T cells and expanded functional pp65-specific memory cytotoxic T lymphocytes (CTLs)." (PMID 26052526, 2015). "As for patients’ characteristics, it was found that KTR and patients receiving anti-CD25 had a better CD4+ T cell response and control of HCMV infection than HTR or KTR patients receiving ATG." (PMID 25166270, 2014). "In more detail, patients with severe HCMV infection had total or specific CD4+ T-cell levels significantly lower than patients with self-resolving or no infection." (PMID 25166270, 2014). "The relatively short time lapse from when HCMV-specific CD8+ T-cells appear to control HCMV infection alone (group 3 patients) is consistently followed by reconstitution of HCMV-specific CD4+ T-cells." (PMID 25166270, 2014). "Pertinent to this study, it has been shown in the context of HCMV infection that Th1 type gB specific CD4+ T cells that secrete IFNγ and TNFα have also been shown to be able to mediate MHC class II restricted cytotoxicity." (PMID 24130479, 2013). "The study investigates the prevalence of individuals with an inverted CD4/CD8 ratio as well as data on T and B cell subsets, CMV infection, and gender, which were previously found to be associated with an IRP in very old individuals." (PMID 22415616, 2013). "A role of CD4 T cells in providing help to CD8 T cells during CMV infection was already proposed a decade ago by studies carried out in HIV-1-infected patients." (PMID 23717308, 2013). "Only 5/93 (5%) patients, after reaching the level of CD4+ T-cells >0.4/μl blood were given pre-emptive therapy to control HCMV infection." (PMID 22848556, 2012). "It is now firmly established that long-term latent HCMV infection is very efficiently controlled by virus-specific CD4+ and CD8+ T cells." (PMID 18806877, 2008).